CDKN2A (cyclin dependent kinase inhibitor 2A)
Diseases named in the same sentence as CDKN2A in open-access papers (continued):
Sharing a sentence is not in itself a finding about the gene and the disease.
tumor (continued). "Moreover, the pRB+ fraction of CDKN2A+ cells correlated with tumor growth; M-Smo/Ezh2cKO tumors, which progressed faster than M-Smo/EedcKO tumors, showed higher pRB+ fractions of CDKN2A+ cells at P12." (PMID 36635771, 2023). "When a tumor was predicted to have A profile by a highest correlation with the A profile reference compared to the H or L profile references, the accuracy of the prediction, based on the exon1α CDKN2A contribution, raised to 98.2%." (PMID 37964967, 2023). "Correlating MD to NE tumor regions harboring EGFR amplification/CDKN2A deletion offers a means to assess regional cell proliferation, and identifying foci of cell proliferation enables a potential translational capability to implement targeted localized therapies." (PMID 37770427, 2023). "This confirms that SHE cells are more representative of human cell behavior than mouse cells and means that CDKN2A hypermethylation and p16 silencing are suitable biomarkers to understand the early events following human chemical exposure, in relation to tumor progression." (PMID 36982734, 2023). "Varying tumour classifications have been used to describe the effect of CDKN2A/B HD." (PMID 37504251, 2023). "We suggest that in the context of a functioning CDKN2A gene, aberrant tumor cell proliferation may result in incrementally increasing, compensatory expression of CDKN2A/p16 in a futile effort to halt cell cycle progression." (PMID 37093270, 2023). "Indeed, observation of less than 5% p16-positive tumor cells predicted a homozygous deletion of CDKN2A with a sensibility of 100%, a specificity of 71%, a positive predictive value of 50%, and a negative predictive value of 100%." (PMID 36900302, 2023). "Nonetheless, few investigations in recent decades have searched for mutations in other genes, such as CDKN2A, PTEN and AKT1, which could provide more knowledge regarding this tumor’s resistance and etiopathogenesis." (PMID 37368773, 2023). "Possible explanations for this discrepancy may be attributed to changes in CDKN2A protein transcription and translation, as well as tumor heterogeneity." (PMID 37950153, 2023). "NE tumor populations predicted to display increased cellular proliferation by mean diffusivity (MD) MRI metrics are uniquely associated with EGFR amplification and CDKN2A homozygous deletion." (PMID 37770427, 2023). "Functionally, we demonstrated that the silencing of SIX1, SIRT2 and CDKN2A expression could accelerate the migratory and invasive capacities of tumor cells, whereas the downregulation of PGR dramatically inhibited cancer cells migration and invasion." (PMID 37723477, 2023). "Altering current model systems could also extend to determining the contribution of secondary mutations besides CDKN2A to EHE development, as it is conceivable that these would affect tumour growth to varying degrees." (PMID 37296967, 2023). "However, as a tumor suppressor gene, the expression levels of CDKN2A were upregulated in many cancer types." (PMID 36647100, 2023). "The role CDKN2A plays as a tumor suppressor is contradicted by this finding." (PMID 37950153, 2023). "In all models, tumours were classified as grade 4 if CDKN2A/B HD was present." (PMID 37504251, 2023).
tumor (continued). "Numerous studies have proven that methylation or dysregulation of ANRIL may lessen CDKN2A / B and its downstream tumor suppressants (p14ARF and p16INK4A), which main to tumor formation and progression." (PMID 37845622, 2023). "We found that under several forms of human cancers, CDKN2A was highly expressed in cancerous tissue in comparison to healthy one and this feature was correlated with poor clinical outcome and positively correlated with the tumor stage, grade, and metastasis." (PMID 37626750, 2023). "MTAP deletion without CDKN2A co-deletion did not occur in any of the PM tumor samples, and loss of MTAP expression occurred exclusively in conjunction with loss of p16 labeling." (PMID 37894345, 2023). "We found that PDHA1 was downregulated and CDKN2A was upregulated in the tumor samples." (PMID 37711156, 2023). "Multivariate analysis indicated that poor differentiation (multivariate OR = 3.82, 95% CI = 1.41–12.2, P = 0.008) and CDKN2A/p16 alteration (multivariate OR = 2.06, 95% CI = 1.08–4.02, P = 0.046) were independent predictors of a low tumor-stromal collagen amount in PDAC." (PMID 37477731, 2023). "Additionally, CDKN2A experienced different forms of genetic alteration under tumor conditions, a characteristic that influenced the infiltration and the status of CD8, the chemokine CCL4, and the chemokine receptor CCR6." (PMID 37626750, 2023). "Also of interest was the 9p21 locus, which contains the prominent tumor suppressor CDKN2A, MTAP, as well as a cluster of IFN genes and has been linked to ICI resistance in pan-tumor studies." (PMID 36977461, 2023). "The mouse xenograft models were established to determine whether CDKN2A contributes to tumor progression in vivo." (PMID 36581816, 2022). "We found that co‐deletion of IFN‐I and CDKN2A or CDKN2B was associated with poor clinical outcomes and downregulated expression of genes related to inflammatory response, adaptive immune response, and JAK‐STAT signaling in the tumor microenvironment." (PMID 35253368, 2022). "Notably, the high-risk group presented overexpression of three cuproptosis biomarkers: CDKN2A, DLD, and DLAT; moreover, tumor tissues of this group have more tumor mutation burden and less immune cell infiltration." (PMID 36003780, 2022). "CDKN2A is involved in tumorigenesis of HNSCC tumors and encodes tumor suppressors." (PMID 35563463, 2022). "Similar results were obtained in this study, indicating that CDKN2A plays an important role in regulating the tumour cell cycle and may serve as a prognostic marker in HNSCC." (PMID 36699463, 2022).
tumor (continued). "Also, PIK3CA overtook MYC as the top CNA-based oncogene, and PTEN displaced CDKN2A from the top CNA-based tumour suppressor spot." (PMID 35975235, 2022). "A limited number of studies have investigated the role of p19Arf in the context of the ISR pathway, with one study showing that deletion of the ISR-regulated gene ATF4 increased the expression of the CDKN2A genes p16Ink4a and p19Arf suppressing colony formation and tumor growth." (PMID 34994382, 2022). "This tumor showed preserved expression of mTAP by IHC, and CDKN2A FISH revealed normal results." (PMID 35565429, 2022). "Loss of function of CDKN2A is a common event not only in the initial phases of carcinogenesis but also in the negative evolution of neoplasia." (PMID 35456025, 2022). "CDKN2A is a tumor suppressor that renders the retinoblastoma inactive." (PMID 35956100, 2022). "It is not known if MMe tumor cells from Cdkn2a+/−;Nf2+/− mice have any replication repair deficiency." (PMID 35804881, 2022). "ACTR5/IES6 promotes tumor progression via epigenetic silencing of CDKN2A." (PMID 36563143, 2022). "Thus, with deletion, mutation, or genetic polymorphisms of CDKN2A, the expression and effectiveness of p16INK4A and p14ARF tumor suppressors are decreased, leading to deregulation of cell proliferation and cancer development." (PMID 35932035, 2022). "CDKN2A expression differed considerably between tumor and normal tissues in our investigation." (PMID 36186479, 2022). "In this study, mutations in the genes ARID1A, APC, ERBB4, NCOR1, PDGFRA, ATM, and CDKN2A were either non-recurrent or of very low frequency, while none of the 14 sequenced EP tumours harboured mutations in the genes HRAS, EGFR, or RB1." (PMID 34045664, 2022). "Cdkn2a is a cyclin-dependent kinase inhibitor that functions as a tumor suppressor." (PMID 35324997, 2022). "BRAF, ATRX, IDH1, and CDKN2A showed significant SNV alterations in most tumour types." (PMID 36186436, 2022). "Patients who have tumor chromosomal CDKN2A deletion are prone to immunotherapeutic resistance." (PMID 36860211, 2022). "MTAP is a tumor suppressor gene near CDKN2A and can be co-deleted in cancer cell lines." (PMID 35764172, 2022). "No PIK3CA or CDKN2A variants were detected in the 9 paraffin-embedded tumor specimens in this study." (PMID 36289533, 2022). "Herein, we show that the type I IFN cluster is co-deleted with CDKN2A/B in nearly half of all tumors harboring 9p21.3 deletions and, while other 9p21.3 genes such as Mtap46 may also influence tumor behavior, type I IFNs are critical tumor suppressors." (PMID 36344707, 2022). "The mutation frequencies of several tumor-suppressor genes including FAT1, CDKN2A, FGFR3, and CASP8 were lower in the HPV-positive group of HNSC, and even the mutation frequencies of FAT1, CDKN2A, and CASP8 were 0, indicating that the biological processes regulated by these genes were not disrupted." (PMID 35392231, 2022).
tumor (continued). "This research result indicated CDKN2A might function as a tumour suppressor in PTC, but the autophagy mediated by CDKN2A effect on the thyroid has not been reported until now." (PMID 35459137, 2022). "To further confirm the potential of our reconstruction method for the detection of expanding cell clones harboring multiple IS in a polyclonal setting, we took advantage of a preclinical model of HSC gene therapy (GT) based on tumor-prone Cdkn2a-/- Lineage- (Lin-) cells." (PMID 35764632, 2022). "In addition to the high expression of CDKN2A in tumor tissue, the rest of the genes showed low expression in tumors." (PMID 36209249, 2022). "Through multi-omics analysis, the exploration of the mechanism of immunity and ferroptosis in the occurrence, development and prognosis of THCA from the aspects of anti-tumor immunity, CDKN2A-related ceRNA regulation, CNV and high-frequency gene mutation will also provide many scientific values." (PMID 36060256, 2022). "Our study found seven downstream factors that may be associated with chemoresistance, LTF, SOD2, STAT1, CDKN2A, CD81, RAC1, and NDRG1 and five factors that may be associated with tumor development, CCN1, DCTN3, MUC1, H1-5, and SLC1A5." (PMID 35421932, 2022). "As a threshold for detection of CDKN2A homozygous deletion in a tumor DNA sample, we used a copy number value of 0.5, which could reliably detect a homozygous deletion in a background of less than 25% non-deleted cells, i.e., a tumor cell content of ≥ 75%." (PMID 35361262, 2022). "p14ARF protein (encoded by CDKN2A gene—Cyclin-Dependent Kinase 4 Inhibitor A) is an important tumour suppressor gene, frequently mutated or deleted in many types of tumours." (PMID 35054835, 2022). "CDKN2A is a tumour suppressor gene located on chromosome 9p21." (PMID 36505786, 2022). "Aberrant DNA methylation was assessed for four genes—p16 (CDKN2A), O6-methylgua-nine-DNA-methyltransferase (MGMT), glutathione S-transferase P1 (GSTP1), and death-associated protein kinase (DAP-kinase)—in both primary tumor and serum of 50 HNSCC patients." (PMID 35406495, 2022). "After multivariable adjustment for clinical and tumor features (see “Methods”), CDKN2A deletion remained predictive of survival after mono-IO treatment with an adjusted hazard ratio of 1.9 [1.3–2.7] and 1.1 [0.8–1.4] for mono-IO and chemo-IO cohorts respectively." (PMID 35739333, 2022). "INK4 expression accurately distinguished tumor from normal tissue, particularly CDKN2A and CDKN2C." (PMID 35771229, 2022). "We interpret our observations to mean that immunoediting occurs under selective pressure by which certain tumor subclones transform to a less immunogenic phenotype through HLA LOH and CDKN2A/B loss, and that this subclonal selection can produce a highly heterogenous TME." (PMID 36536472, 2022). "Although not yet tested in GEP-NENs, loss of the enzyme methylthioadenosine phosphorylase (MTAP) due to genetic deletion of the nearby CDKN2A tumor suppressor may confer dependence on PRMT5 arginine methyltransferase activity as happens in other cancers." (PMID 35747820, 2022). "CDKN2A/BHDIFN‐IHD had downregulated several key immune response pathways, suggesting that poor prognosis in CDKN2A/BHD LUAD could potentially be attributed to an immunosuppressive tumor microenvironment as a result of IFN‐I depletion." (PMID 35253368, 2022).
tumor (continued). "We observed various responses to palbociclib concerning both models (CD3, CD7) harboring a loss of CDKN2A/2B, and no tumor efficacy in the non-CDKN2A/2B-deleted PBRM1-mutated PDX (CD39)." (PMID 36505864, 2022). "Prognostic CRGs, especially CDKN2A, the independent factor of HCC prognosis, may be closely associated with immune-cell infiltration, tumor mutation burden (TMB), microsatellite instability(MSI), and immune checkpoints." (PMID 36588699, 2022). "There is extensive evidence that promoter hypermethylation leads to the silencing of specific tumour suppressor genes in MF/SS including those involved in cell cycle regulation (CDKN2A/2B), DNA repair (MLH1 and MGMT), apoptosis (FAS) and JAK-STAT signalling (SHP-1)." (PMID 36505788, 2022). "Pro-tumorigenic tumors displayed upregulation of genes related to pro-tumoral processes such as adhesion or migration (NCAM1), proliferation (CDK1, TOP2A) or extensively described tumor markers (CDKN2A, MTOR), among others, while showing an impairment in immune-related functions." (PMID 35329826, 2022). "In addition, HPV-negative tumors often show amplification of 11q13 including CCND1 and focal deletions of tumor suppressor genes including CDKN2A." (PMID 35884529, 2022). "The essential tumor suppressor Cdkn2a gene (Ink4a) is the main regulator of pRb1." (PMID 36234520, 2022). "However, some cuproptosis-associated genes, including MTF1, GLS, and CDKN2A, were positively associated with immune, stromal, and ESTIMATE scores, and the levels of immune and stromal cells were high across cancers, with low tumor purity." (PMID 36105090, 2022). "This suggests that CDKN2A is involved in tumor immune microenvironment homeostasis." (PMID 36699463, 2022). "The most common alterations were BAP1 mutations (n = 5; of note, BAP1 was assessed only by the 14MG panel and only in the tumour specimen, no germline analysis), CDKN2A loss (n = 2) and NF2 mutation (n = 2; to note, NF2 was assessed only by the 14MG panel)." (PMID 35585228, 2022). "CDKN2A was highly expressed in tumor patients and correlated with prognosis." (PMID 36132144, 2022). "Shared biallelic NF1 inactivation was present in all three tumor pairs, as well as shared CDKN2A homozygous deletion and ATRX mutation in two tumor pairs each, thereby indicating these were initiating truncal events critical to gliomagenesis in the setting of NF1." (PMID 35945463, 2022).